ENO1 (enolase 1)
Diseases named in the same sentence as ENO1 in open-access papers (continued):
Sharing a sentence is not in itself a finding about the gene and the disease.
cancer (305 papers, 2008 to 2026). A tumor composed of atypical neoplastic, often pleomorphic cells that invade other tissues. "In summary, this section integrates risk profiling, pan-cancer characterization, and in vitro functional assays to highlight ENO1 as a biologically and clinically relevant component of the NMRS." (PMID 41514669, 2026). "Overexpression of ENO1 is mainly associated with chemoresistance, poor prognosis, reduced survival and stemness in cancers." (PMID 41154605, 2025). "The alpha-enolase (ENO1) variant has diverse roles beyond glycolysis, including stress response, infection, cancer progression, and reproduction." (PMID 41303481, 2025). "The expression of ENO1, regulated by ncRNAs, is associated with glycolysis-mediated cancer chemoresistance." (PMID 40264038, 2025). "Through structural analysis and experiments, it has been proven to be an efficient nanomolar-level enolase inhibitor that has potential value in the treatment of cancers with ENO1 deficiency." (PMID 40507914, 2025). "Glycolysis-regulating genes such as SOX9, ABCB6 and ENO1, were associated with metabolic reprogramming essential for cancer progression." (PMID 39920655, 2025). "The relevance of ENO1 in cancer goes beyond its diagnostic and prognostic value, encompassing important therapeutic perspectives." (PMID 41179678, 2025). "The activation of the ENO1 signaling pathway has been linked to glycolysis and drug resistance in various cancers 14-16." (PMID 41049005, 2025). "Previous studies have reported ENO1 overexpression in several cancers, including breast, neck, lung, prostate, and gastric cancer, where it is closely linked with cancer progression and poor patient prognosis." (PMID 40821642, 2025). "Network analysis of the main cancer hallmarks and their associated pathways identified that ENO1 clusters with many signalling, epigenetic, and immune pathways." (PMID 39483155, 2024). "Studies have confirmed that ENO1 is overexpressed in more than 70% of cancers and is also associated with poor patient outcomes." (PMID 38273010, 2024). "The first reported paralog SL interaction in cancer involves ENO1 and ENO2, encoding the glycolytic enzyme enolase." (PMID 38638566, 2024). "It is overexpressed in many cancers, and in solid tumours, high cellular ENO1 protein and/or mRNA expression has been linked with poor prognosis for lung, breast, pancreatic, and hepatocellular carcinomas." (PMID 38473245, 2024). "Many studies have demonstrated that the localization and overexpression of ENO1 on the cancer cell surface make it a potential prognostic and diagnostic cancer biomarker as well as an accessible oncotarget." (PMID 36588153, 2023). "ENO1 overexpression and post-translational modifications were observed to have diagnostic and prognostic value in many cancer types." (PMID 36553191, 2022). "This work is of significance for further revealing H. pylori pathogenic mechanism and for formulating novel diagnostic and therapeutic strategies targeted at ENO1 for gastric precancer lesions and cancer." (PMID 36295613, 2022). "Survival analysis revealed that overexpression of ENO1 was associated with shorter cancer-specific overall survival and shorter disease-free survival." (PMID 35204345, 2022). "It has been reported that these genes were closely associated with cancer progression, including ENO1, PRKCB, ENO2, and PDK1." (PMID 35504868, 2022). "The localization of ENO1 on the cell surface makes it an ideal prognostic and diagnostic cancer biomarker." (PMID 35434271, 2022). "It has been discovered that ENO1 expression levels were associated with tumorigenesis, proliferation, metastasis, and stem cell-like properties in various types of cancer." (PMID 36620599, 2022). "ENO1 overexpression has been demonstrated in a wide range of human cancers and is often associated with poor prognosis." (PMID 36620599, 2022). "ENO1 is a multifunctional protein which implicated in critical biological progression pathways in cancers." (PMID 35844805, 2022).
cancer (continued). "ENO1 overexpression is observed in several cancer types, and is known to be associated with cancer cell stemness." (PMID 34681284, 2021). "ENO1 has been found to be overexpressed in more than 10 types of human cancer, and is related with metabolic reprogramming of cancer cells and cancer associated transduction cascades." (PMID 34671213, 2021). "And, ENO1 is released into the extracellular space in the form of exosomes, and exosomal ENO1 associate with the metastatic potential of cancer cells." (PMID 34671213, 2021). "ENO1 is a glycolysis-associated enzyme that participates in various cancers; therefore, we focused on glycolysis-associated pathways; the mTOR/HIF1α pathway is also involved in glycolysis." (PMID 33968941, 2021). "Regarding Eno1, its high expression is associated with aggressive cancer, and its deletion is reported to suppress the growth and migration by inactivating PI3K signaling." (PMID 34830748, 2021). "Potential prognostic and diagnostic value of ENO1 expression in tumors and cancer-associated anti-ENO1 autoantibodies." (PMID 33584813, 2020). "During inflammatory conditions, plasmin activation leads to fibrinolysis and facilitates extracellular matrix degradation, a function linked to ENO1’s ability to promote cancer cell migration, invasion, and metastasis." (PMID 33584813, 2020). "ENO1 overexpression has been established in a broad range of human cancers and is often associated with poor prognosis." (PMID 33584813, 2020). "Increased ENO1 expression is observed in many types of malignant tumors and is associated with aggressive phenotypes." (PMID 30967137, 2019). "ENO1 is a multifunctional protein that has been implicated in several critical biological progresses in cancer, including the proliferation, migration, and invasion." (PMID 30518748, 2018). "Studies have revealed that high level of ENO1 was strongly linked to poor prognosis of cancer patients." (PMID 28548950, 2017). "Extracellular or cell surface ENO1 was suggested to act as a plasminogen receptor mediating extracellular matrix degradation and cell migration in cancer and to have diagnostic and prognostic values." (PMID 26486078, 2015). "In addition, we review studies that evaluate the association between ENO1 expression and patient prognosis in pan-cancer datasets and individual malignancies." (PMID 42196455, 2026). "ENO1, a key glycolytic enzyme with multifaceted intracellular and extracellular functions, has been implicated in proliferation, migration, angiogenesis, and immune evasion across various cancers." (PMID 41514669, 2026). "ENO1 is widely recognized for its role in promoting the Warburg effect in cancer cells, and its overexpression is associated with poor prognosis in various cancers, including GC." (PMID 40730815, 2025). "ENO1 has been implicated in several cancer types, showing relevance in oncological studies." (PMID 40005870, 2025). "The biological processes related to cancer development, signaling, and response comprised 12 distinct hallmark pathways enriched with genes related to hypoxia, including Enolase 1 (ENO1), Triosephosphate isomerase (TPI-1), Decorin (DEC) Fos- proto-oncogene gene (FOS), and Aldolase-(ALDO)." (PMID 39063015, 2024). "Consequently, the activity of ENO1 is enhanced in response to the heightened glucose consumption associated with cancer malignancy." (PMID 37741973, 2023). "Several studies on cancers have indicated that an increased level of ENO1 may be associated with the tumorigenic process." (PMID 36768425, 2023). "In fact, upregulation of ENO1 is associated with worse prognosis in many cancer types, which may in part be mediated by chemotherapy-induced nuclear translocation of MCL1 to drive chemoresistance, possibly through the regulation of transcription." (PMID 35042842, 2022). "ENO1 maintains “aerobic glycolysis and can causes autoantibody genesis in cancer patients." (PMID 36077431, 2022).
cancer (continued). "The expression levels of ENO1 are closely associated with several diseases, including Alzheimer's disease 6, diabetes 7, hypoxic-ischemic encephalopathy 8, as well as some types of cancers 9-16." (PMID 34671213, 2021). "ENO1 and antibody of ENO1 in the serum is associated with the clinical stage of cancer." (PMID 34671213, 2021). "For instance, the expression of α-enolase (ENO1), a glycolytic enzyme that converts 2-phosphoglycerate into phosphoenolpyruvate, is upregulated in hypoxic conditions and cancer cells and is associated with poor prognosis in various types of cancers." (PMID 34136381, 2021). "Beyond cancer, ENO1 has been implicated in autoimmune and inflammatory diseases." (PMID 31511554, 2019). "The increased levels of both ROS and GLS activity after ENO1 silencing prompted us to investigate whether ENO1-deficient cancer cells could be sensitized to the inhibition of anabolic glutamine metabolism." (PMID 26734996, 2016). "Both enolase-1 over expression and its post-translational modifications could be of diagnostic and prognostic value in cancer." (PMID 23845056, 2013). "Notably, dysregulation of ENO1 has been associated with several cancers." (PMID 36845730, 2023). "As a hub gene of signature identified by PPI network, ENO1 is overexpressed in 70% of human cancers and is associated with poor cancer prognosis, converts 2-phosphoglycerate to phosphoenolpyruvate, plays an important role in the glycolytic pathway and the Warburg effect in cancer cells." (PMID 38097352, 2023). "Hence, targeting extracellular ENO-1 may be beneficial not only in the treatment of cancer patients, but also in infectious diseases caused by multiresistant strains and in chronic autoimmune diseases." (PMID 31106201, 2019). "Through pan-cancer analyses and in vitro validation, we further confirmed the functional relevance of key metabolic drivers such as ENO1." (PMID 41514669, 2026). "This review summarizes the current knowledge regarding the biological and clinical significance of ENO1 across multiple cancer types." (PMID 42196455, 2026). "The functional relevance of the key gene ENO1 was further verified through pan-cancer analyses and in vitro experiments." (PMID 41514669, 2026). "ENO1, markedly upregulated in high-NMRS tumors and functioning as a risk factor in several cancer types, was experimentally shown to promote invasion in LUAD cell lines." (PMID 41514669, 2026). "To investigate the broader relevance of ENO1, we conducted a pan-cancer Cox regression analysis across TCGA cohorts." (PMID 41514669, 2026). "In this study, ENO1 was markedly upregulated in the NMRS-high group and identified as a risk factor across multiple cancer types in a pan-cancer analysis." (PMID 41514669, 2026). "We further examine the evidence linking ENO1 to major cancer-related processes, including proliferation, apoptosis resistance, cancer stemness, autophagy, metastasis, drug resistance, and angiogenesis." (PMID 42196455, 2026). "Alpha-enolase (ENO1) is a multifunctional protein best known for its canonical role in glycolysis, but growing evidence indicates that it also plays important roles in cancer development and progression." (PMID 42196455, 2026). "It is worthwhile emphasizing that the consistent link between elevated ENO1 levels in various cancers and poor clinical outcomes highlights its essential role in triggering cancer-promoting pathways, making it an ideal candidate for therapeutic intervention." (PMID 40740998, 2025). "In the present study, the nuclear staining of ENO1 was observed in 16 malignant tumor samples, 9 of which belonged to patients with a good prognosis and 7 of which had a death outcome." (PMID 41179678, 2025). "Glycolytic enzymes such as LDHA, PKM2, HK2, and ENO1, along with nutrient transporters like GLUT1, ASCT2, and LAT1, are consistently upregulated across multiple cancer types and have been linked to poor prognosis and therapy resistance." (PMID 41154605, 2025).
cancer (continued). "ENO1 functions as a multifunctional oncoprotein contributing to seven of the ten hallmarks of cancer." (PMID 40486495, 2025). "This fact corroborates studies that report the expression of ENO1 on the cell surface exceptionally in malignant tumors, where it binds to plasminogen to promote ECM degradation and metastasis." (PMID 40005870, 2025). "The overexpression of ENO1 is closely related to the proliferation, migration, and invasion abilities of cancer cells." (PMID 41231037, 2025). "This study investigated the immunohistochemical expression of ITIH2 and ENO1 in mammary tissues from healthy dogs and those with benign and malignant tumors." (PMID 40005870, 2025). "Specifically, ENO1 promotes choline phospholipid metabolism by stabilizing choline kinase-α, thereby supporting cancer cell proliferation." (PMID 40933559, 2025). "ENO1’s cell surface localization and cancer-specific overexpression make it a promising and accessible biomarker for diagnosis and prognosis, as well as a therapeutic target." (PMID 41373732, 2025). "ENO1, an enzyme that plays a vital role in glycolysis, is ubiquitous in most human tissues and highly expressed in numerous cancers." (PMID 40740998, 2025). "ENO1 is one of the key enzymes in glycolysis and an oncogenic protein with diverse functions, overexpressed in most human cancers." (PMID 40507914, 2025). "ENO1 is a central driver of cancer metabolism, progression, and immune modulation, making it a promising candidate for integrated diagnostic, prognostic, and therapeutic strategies in oncology." (PMID 41373732, 2025). "Like the multifunctional roles of ENO1 in promoting cancer cell proliferation, invasion, and metastasis, we also observed these biological characteristics in GC cells overexpressing ENO1." (PMID 41168198, 2025). "Among the four isoforms of enolase, ENO1 is widely expressed in most human tissues and is overexpressed in various cancer types." (PMID 40775002, 2025). "Although ENO1 has been extensively investigated in cancer biology, its involvement in CNS inflammation such as EAE and MS has not been elucidated." (PMID 40332313, 2025). "Among the ENO isoforms, ENO1 and ENO2 have been identified in EVs associated with cancers of the breast and prostate." (PMID 40214422, 2025). "As a conclusion regarding the expression of ENO1, we can state that we are certain of its membrane expression exclusively in malignant tumors." (PMID 40005870, 2025). "Beyond its metabolic role, ENO1 functions as a plasminogen receptor on the surface of cancer cells, facilitating extracellular matrix degradation, cell invasion, and metastasis." (PMID 40005870, 2025). "MiR-22 modulates key metabolic genes including ATP citrate lyase (ACLY) and enolase 1 (ENO1) in different cancer types, suggesting its prominent role in modulating the so-called “Warburg effect”." (PMID 40332478, 2025). "ENO1, a glycolytic enzyme, plays crucial roles in multiple pathological processes, particularly cancer development." (PMID 40740783, 2025). "ENO1 is overexpressed in various cancers, and its upregulation drives tumorigenesis and metastasis by modulating the AMPK/mTOR signaling pathway." (PMID 40734168, 2025). "Enolase 1 (ENO1) is a glycolytic enzyme that plays a crucial role in cancer progression via cell death regulation, epithelial‐to‐mesenchymal transition, and metabolism reprogramming." (PMID 41328768, 2025). "ENO1 is overexpressed in a wide range of tumors and its biological implications in cancer have been extensively studied." (PMID 40573960, 2025). "Our results showed that ENO1 was detected in both benign and malignant tumors, which was expected as it is an enzyme present throughout the body and essential in the cellular respiration mechanism." (PMID 41179678, 2025). "ENO1, a key enzyme in the glycolytic pathway, plays a critical role in regulating glycolysis and has been recognized as a promising therapeutic target in cancer." (PMID 40730815, 2025).
cancer (continued). "We propose novel insight into comprehensive cancer metabolism regulation: ENO1 enhances glycolysis, leading to the substantial production of ATP and lactate, which further elevates the intracellular ATP pool and lactate homeostasis." (PMID 41168198, 2025). "In our study, four glycolysis genes (ENO1, STMN1, PKM, and CDK1) have been previously reported to be associated with cancer progression and drug resistance." (PMID 38840205, 2024). "Studies have also shown that ENO1 expression correlates with poor prognosis of cancer patients, implicating a potential as a prognostic biomarker." (PMID 38611852, 2024). "N. fowleri is remarkably sensitive to one such inhibitor, HEX, with EC50 values about 6-fold lower than those required to kill ENO-1-deficient GBM cells, the cancer type that was the target of the initial phosphonate design campaign." (PMID 39088549, 2024). "Among the three enolase isoforms, both enolase 1 (ENO1) and ENO2 encode crucial glycolytic metalloenzymes and are frequently associated with metastases and unfavourable prognoses in multiple cancer types." (PMID 39061144, 2024). "ENO1 is the most extensively studied, with its role and mechanisms in cancer development having been thoroughly reviewed previously." (PMID 39061144, 2024). "Another highly abundant protein found mostly in the malign carcinoma group was phosphopyruvate hydratase or alpha enolase (ENO1), which plays a crucial role in cancer development by promoting cell proliferation, invasion and metastasis." (PMID 39061201, 2024). "ENO1 is involved in glycolysis and its gene expression has been reported to be dysregulated in various cancer types." (PMID 39239354, 2024). "ENO1, as the classical enzyme, plays a crucial role in glucose metabolism and cancer development, while high expression of NSUN2 leads to the reprogramming of glucose metabolism via m5C modification of ENO1 in CRC." (PMID 38769664, 2024). "In cancer metabolic reprogramming, ENO1 stimulates cancer cells to create energy largely through the breakdown of glucose in a non-oxidative way, rather than typical oxidative phosphorylation, which is known as the Warburg effect." (PMID 39061201, 2024). "ENO1 is a multifunctional glycolytic enzyme and oncoprotein that exists as a plasminogen receptor on the cell surface and is involved in most of the ‘cancer hallmarks’." (PMID 39245797, 2024). "ENO1 has attracted extensive attention due to its involvement in the regulation of CSCs-like characteristics of cancer cells." (PMID 38515460, 2024). "We used the CPTAC database to explore the phosphorylation sites and ENO1 protein levels in Pan-cancer." (PMID 39576845, 2024). "ENO1 is overexpressed in multiple cancers, including MM, and is regarded as a potential target for cancer therapy." (PMID 39682151, 2024). "We analyzed the phosphorylation levels of ENO1 in regular and initial carcinoma tissues using the CPTAC database." (PMID 39576845, 2024). "Similar to cancer, inhibition of Eno1 leads to markedly depressed osteogenic differentiation, suggesting the potential role of Enol in regulating osteogenic differentiation." (PMID 37125075, 2023). "We mainly validated the biological functions of ENO1 in PDAC cells by examining “loss-of-function”, while “gain-of-function” studies can further uncover the mechanism of ENO1 activating intracellular and extracellular signals in cancer cells." (PMID 36845730, 2023). "The prognostic value of ENO1 expression level in human cancers was analyzed using the Kaplan-Meier plotter database." (PMID 36845730, 2023). "Currently, extensive studies have shown that ENO1 is regulated by different mechanisms, thereby regulating the progress of cancer by affecting the glycolysis pathway." (PMID 36999124, 2023). "ENO1 also regulates gene transcription and translation in cancer cells by displaying multiple binding capacitates to DNA and mRNA." (PMID 37444523, 2023).